SLC38A4 (solute carrier family 38 member 4)
Description:
Symporter that cotransports neutral amino acids and sodium ions from the extracellular to the intracellular side of the cell membrane. The transport is electrogenic, pH dependent and partially tolerates substitution of Na(+) by Li(+). Preferentially transports smaller amino acids, such as glycine, L-alanine, L-serine, L-asparagine and L-threonine, followed by L-cysteine, L-histidine, L-proline and L-glutamine and L-methionine.
Synonyms: ATA3; NAT3; SNAT4; PAAT
Tractability: Antibody: UniProt places it where antibodies can reach, with high confidence; its Gene Ontology location is reachable by antibodies, with high confidence; UniProt predicts a signal peptide or a membrane-spanning region. PROTAC: its protein half-life has been measured.
Gene: Protein-coding gene on chromosome 12 (46,763,642 to 46,832,500, reverse strand). Ensembl gene ENSG00000139209.
Subcellular location: Cell membrane; Cell projection, microvillus membrane
Pathways (Reactome):
Transport of small molecules: Amino acid transport across the plasma membrane
Gene Ontology:
Molecular function: alanine:sodium symporter activity; amino acid:sodium symporter activity; glycine:sodium symporter activity; L-asparagine:sodium symporter activity; neutral L-amino acid:sodium symporter activity; protein binding; amino acid transmembrane transporter activity; L-amino acid transmembrane transporter activity; proline:sodium symporter activity; L-arginine transmembrane transporter activity
Biological process: L-alanine import across plasma membrane; neutral amino acid transport; amino acid transmembrane transport; amino acid transport; asparagine transport; glycine transport; L-alanine transmembrane transport; L-arginine transmembrane transport; sodium ion transmembrane transport
Cellular component: microvillus membrane; plasma membrane
Genetic constraint (gnomAD): Loss-of-function variants: 19 observed, 54.73 expected, observed/expected ratio (o/e) 0.35, 90% interval 0.24 to 0.51. The upper end of that interval is the gene's LOEUF score, 0.51, which puts it in group 2 of 6, group 1 being the genes least tolerant of losing a copy. Missense variants: 474 observed, 634.97 expected, observed/expected ratio (o/e) 0.75, 90% interval 0.69 to 0.81. Synonymous variants: 215 observed, 223.53 expected, observed/expected ratio (o/e) 0.96, 90% interval 0.86 to 1.08.
Homologues: Orthologues: chimpanzee SLC38A4 (99% identical), macaque SLC38A4 (97% identical), guinea pig SLC38A4 (91% identical), dog SLC38A4 (89% identical), pig SLC38A4 (88% identical), rat Slc38a4 (88% identical), mouse Slc38a4 (87% identical), rabbit SLC38A4 (79% identical), tropical clawed frog slc38a4 (72% identical), zebrafish slc38a4 (67% identical), Drosophila melanogaster CG32079 (15% identical), Caenorhabditis elegans slc-36.1 (14% identical), and 11 more. Paralogues in human: SLC38A2 (57% identical), SLC38A3 (50% identical), SLC38A1 (47% identical), SLC38A5 (45% identical), SLC38A6 (40% identical), SLC38A11 (20% identical), SLC38A10 (20% identical), SLC38A7 (19% identical), SLC36A4 (19% identical), SLC36A2 (18% identical), SLC36A1 (18% identical), SLC32A1 (16% identical), and 3 more.
Diseases named in the same sentence as SLC38A4 in open-access papers:
SLC38A4 is named in the same sentence as 23 diseases in open-access papers, as found by Europe PMC text mining. Sharing a sentence is not in itself a finding about the gene and the disease. The quoted sentences say what the papers report.
hepatocellular carcinoma (3 papers, 2022 to 2025). A malignant tumor that arises from hepatocytes. "Research has shown that SLC38A4 depletion can repress hepatocellular carcinoma tumorigenesis in vivo." (PMID 35321408, 2022). "In addition, studies have confirmed that SLC38A4 is a prospective biomarker with therapeutic goal that exerts tumor suppressive effects in hepatocellular carcinoma by modulating the Wnt/β-catenin/MYC/HMGCS2 axis." (PMID 37168445, 2023). "SLC38A4 can inhibit hepatocellular carcinoma (HCC) progression." (PMID 40892354, 2025).
hyperglycaemia (2 papers, 2017 to 2024). "It is believed that this protein plays a significant role in gluconeogenesis, since SNPs in the SLC38A4 gene are found to be associated with hyperglycemia." (PMID 29297313, 2017). "The most relevant CpG site (cg14671384, P = 9.09 × 10–9) locates in the promoter of the SLC38A4 gene (Solute Carrier Family 38 Member 4), which has been reported to be a transporter of cationic and neutral amino acids and closely related with glucagon and hyperglycaemia." (PMID 38802969, 2024).
liver cancer (2 papers, 2023 to 2024). An epithelial or non-epithelial malignant neoplasm that arises from the liver. "SLC38A4 has been identified in liver cancer as a tumor-suppressor gene that inhibits cell proliferation, promotes cellular apoptosis, and its molecular event of silencing serves as an oncofetal event." (PMID 39114022, 2024). "The ectopic expression of the ED_miR-3144(3_A < G) mimic suppressed SLC38A4 protein expression, whereas an antisense ED_miR-3144(3_A < G) mimic rescued SLC38A4 expression in liver cancer cells (upper)." (PMID 36599932, 2023). "In this study, we investigated the oncogenic function of ADAR1 by promoting miR-3144-3p editing to simultaneously induce Musashi RNA-binding protein 2 (MSI2) and suppress solute carrier family 38 member 4 (SLC38A4) in human liver cancer." (PMID 36599932, 2023). "The ectopic expression of both ADAR1 and the ED_miR-3144-3p(3_A < G) mimic enhanced mitotic activities, and ADAR1 suppressed SLC38A4 expression in liver cancer cells." (PMID 36599932, 2023). "When MIHA and SNU-449 cells were transfected with a ED_miR-3144 (3_A < G) mimic or pcDNA3.1_ADAR1-p110_wild in the presence of primary mir-3144, only the expression of the SLC38A4 candidate target gene was inhibited in both liver cancer cell lines." (PMID 36599932, 2023). "Next, we aimed to confirm our finding that the potential target of ED_miR-3144(3_A < G) is SLC38A4 in liver cancer cells." (PMID 36599932, 2023). "Treatments with mouse-specific ADAR1-, MSI2-siRNA-, or SLC38A4-expressing plasmids suppressed tumorigenesis and tumor growth in a mouse model of spontaneous liver cancer." (PMID 36599932, 2023). "DNA hypermethylation leading to reduced regulation of SLC38A4 aids in liver cancer." (PMID 39114022, 2024). "Reduced SLC38A4 expression was accompanied by poor prognosis in liver cancer patients." (PMID 39114022, 2024). "Our analyses showed the downregulation of SLC38A4 in large cohorts of liver cancer patients." (PMID 36599932, 2023). "However, SLC38A4 has been reported to function as a tumor suppressor in liver cancer through its modulation of Wnt/β-catenin/MYC/HMGCS2 axis acativation." (PMID 36599932, 2023). "Next, to demonstrate whether individual modulation of ADAR1, MSI2, and SLC38A4 affects liver tumorigenesis in vivo, we prepared H-ras-transgenic mice that spontaneously develop liver cancer beginning at ~14 weeks of age13." (PMID 36599932, 2023). "In addition, ADAR1-dependent excessive editing of canonical miR-3144-3p leads to the generation of a novel ED_miR-3144(3_A < G) mutant that specifically suppresses SLC38A4 mRNA translation to inactivate the tumor suppressor function of SLC38A4 during liver cancer progression." (PMID 36599932, 2023). "Therefore, we predicted that MSI2, a Musashi RNA-binding protein, as a target of canonical miR-3144-3p and SLC38A4 (solute carrier family 38 member 4) is a target for edited ED_miR-3144(3_A < G) and performed additional functional studies with these protein in liver cancer." (PMID 36599932, 2023). "On the basis of the expression of the newly edited and generated ED_miR-3144(3_A < G) target gene was reduced as liver cancer progressed, five candidates, INMT, GHR, GLYAT, SLC38A4, and HMGCS2, were identified through target prediction and expression pattern analyses." (PMID 36599932, 2023). "In addition, the ectopic expression of a primary mir-3144 mimic suppressed SLC38A4 protein expression, whereas cotransfection of ADAR1 siRNA with the mimic rescued SLC38A4 expression in liver cancer cells." (PMID 36599932, 2023). "Together, these findings indicated that the SLC38A4 tumor suppressor was inhibited by the ED_miR-3144(3_A < G) mutant generated by excessive ADAR1-dependent miR-3144-3p editing and that these effects contribute to the malignant transformation and growth of liver cancer cells." (PMID 36599932, 2023).
liver cancer (continued). "Notably, we observed a significant positive correlation between MSI2 expression and ADAR1 expression but a negative correlation between SLC38A4 expression reported in publicly available (TCGA_LIHC, ICGC_LIRI, and GSE77314) and our multistage liver cancer (Catholic_mLIHC; GSE114564) datasets." (PMID 36599932, 2023).
lung carcinoma (2 papers, 2016 to 2022). "Furthermore, in a polymorphism study, SLC38A4 rs2429467C >T consistently showed significant associations with lung cancer." (PMID 35321408, 2022).
colorectal cancer (1 paper, 2024). A primary or metastatic malignant neoplasm that affects the colon or rectum. "In conclusion, we suggest that ANO7 and SLC38A4 serve as prognostic biomarkers in colorectal cancer." (PMID 39114022, 2024).
diabetes (1 paper, 2023). "The luminal SLC38A4 transfers neutral and cationic amino acids, such as glutamine and alanine, and its atypical expression is also associated with an increased risk of metabolic diseases such as diabetes, in addition to cancers." (PMID 37238741, 2023).
macrosomia (1 paper, 2023). "The SLC38A4 amino acid transporter, which is crucial for the placental nutrition of the embryo, is overexpressed in the placentas from human foetuses with macrosomia, while its knockout causes foetal weight reduction in mice." (PMID 36870961, 2023).
melanoma (1 paper, 2022). A malignant, usually aggressive tumor composed of atypical, neoplastic melanocytes. "As MeAIB does not just selectively inhibit SNAT1/SLC38A1, but also SNAT2/SLC38A2 and SNAT4/SLC38A4, we further analyzed specific SNAT1 effects using an siPool for selective downregulation of SNAT1 mRNA in melanoma cells." (PMID 35565278, 2022).
Obesity (1 paper, 2024). Accumulation of substantial excess body fat. "Then, we checked the tissue-specific expression of SLC38A4 (where cg14671384 is located) using GTEx and observed that SLC38A4 was significantly overexpressed in liver, which is a tissue highly relevant to obesity and the change of body weight." (PMID 38802969, 2024). "Besides, a previous mouse study observed a decreased body weight in SLC38A4 knock-out mice, supporting a direct role of SLC38A4 in obesity." (PMID 38802969, 2024).
pneumonia (1 paper, 2022). An acute, acute and chronic, or chronic inflammation focally or diffusely affecting the lung parenchyma, caused by an infection in one or both of the lungs (by bacteria, viruses, fungi, or mycoplasma.). "Therefore, SLC38A4 may play a crucial role in pneumonia caused by P. multocida infection." (PMID 35321408, 2022).
preeclampsia (1 paper, 2022). Preeclampsia is a hypertensive disorder of pregnancy that is characterized by new-onset hypertension with proteinuria presenting after 20 weeks of gestation, and depending on mild or severe forms may initially present with severe headache, visual disturbances, and hyperreflexia. "We assessed gene and protein expressions of SLC38A1, SLC38A2, and SLC38A4 in IUGR alone or preeclampsia + IUGR placental samples collected from early preterm (<34 weeks) gestation and compared these to gestationally matched uncomplicated preterm controls." (PMID 36613847, 2022). "SLC38A4 protein was significantly downregulated in early preterm pregnancies complicated with IUGR with/out preeclampsia." (PMID 36613847, 2022). "We next assessed gene and protein expressions of SLC38A1, SLC38A2, and SLC38A4 in IUGR alone or in preeclampsia + IUGR placental samples collected from late preterm (34–36 weeks) gestation and compared these to gestationally matched controls." (PMID 36613847, 2022). "Despite the significant changes to SLC38A4 protein in IUGR and preeclampsia + IUGR placentas, trophoblast hypoxia models did not alter the protein expressions of any of the transporters in vitro." (PMID 36613847, 2022). "Our investigation supports this finding, as the significant reduction in SLC38A4 appear to be an IUGR specific feature, regardless of comorbidities such as preeclampsia." (PMID 36613847, 2022).
tumor (11 papers, 2022 to 2026). "Additionally, multiple anti-tumor drugs were positively associated with SLC38A4 expression." (PMID 40892354, 2025). "SLC38A4 enhances the phagocytosis of various tumor cells by Kupffer cells, leading to a reduction in liver metastasis." (PMID 42067616, 2026). "Here, we identified SLC38A4 expressed on tumor cells as a critical suppressor during tumor liver metastasis." (PMID 42067616, 2026). "This study demonstrates that SLC38A4 promotes Kupffer cell phagocytosis and restricts tumor liver metastasis by suppressing CD24." (PMID 42067616, 2026). "Within the tumor, SLC38A4 exhibited predominantly membranous and cytoplasmic staining, reflecting its role in transporting amino acids." (PMID 40892354, 2025). "Subsequently, the results of RT-qPCR experiments demonstrated that the mRNA expression levels of SLC38A2, SLC38A3 and SLC38A4 were significantly overexpressed in GC tumor tissues." (PMID 36918802, 2023). "HMGCS2 is downregulated in CRC, serving as a critical downstream target of SLC38A4 to regulate tumor cell metabolism." (PMID 35909892, 2022). "While the exact transporters involved in serine uptake within tumours remain incompletely defined, members of the solute carrier (SLC) superfamily, such as SLC1A4 (ASCT1), SLC1A5 (ASCT2), SLC7A10, SLC38A2, SLC38A4 and SLC38A5, have been implicated." (PMID 40660426, 2025). "Generally, the IHC staining patterns of SLC38A4 within the tumor were homogeneous." (PMID 40892354, 2025). "A-to-I editing of miR-3144-3p (3_A < G) by ADAR1 in liver cancer drastically shifts the target specificity of this miRNA, with the defective target of its canonical mRNA target Musashi RBP 2 (MSI2, an oncogene), whereas generating gain-of-function binding to SLC38A4 mRNA (a tumor suppressor)." (PMID 39126156, 2025). "SLC38A4 was found to be a favorable prognostic biomarker and a tumor suppressor gene in CRLM." (PMID 40892354, 2025). "Additionally, the HMGCS2 gene is downregulated in CRC, serving as a critical downstream target for SLC38A4 to regulate tumor metabolism." (PMID 39114022, 2024). "Mechanistically, SLC38A4 downregulates the expression of "don't eat me" molecule CD24, which mediates the roles of SLC38A4 in Kupffer cells phagocytosis and tumor liver metastasis." (PMID 42067616, 2026). "Given the capacity of cancer cells to promote tumor growth by inhibiting immune responses in the progression of CRLM, the role of SLC38A4 in tumor immunity was investigated." (PMID 40892354, 2025). "By analyzing TCGA data in the GEPIA database, we found that the expression levels of multiple SLC38A family members (including SLC38A2, SLC38A4, SLC38A5, SLC38A6, SLC38A7, SLC38A8, SLC38A9, and SLC38A10) were significantly upregulated in GC tumor tissues." (PMID 36918802, 2023). "Western blot analyses confirmed the modulation of Adar1, Msi2, and Slc38a4 expression in the noncancerous liver tissues surrounding tumor masses." (PMID 36599932, 2023).
cancer (7 papers, 2008 to 2025). A tumor composed of atypical neoplastic, often pleomorphic cells that invade other tissues. "Pan‐cancer mutational profiling of SMGs revealed low mutation frequencies in most genes, except for a higher mutation frequency of SLC38A4 in SKCM." (PMID 40660426, 2025). "•Evaluation of survival analysis, methylation, and mutation patterns of ANO7 and SLC38A4 across various cancers." (PMID 39114022, 2024). "We entered the ANO7 and SLC38A4 gene as input and extracted the results of sample samples, cancer stages, gender and histological subtypes in CRC." (PMID 39114022, 2024). "We conducted an analysis of ANO7 and SLC38A4 expression in cancer and normal tissues using data from TCGA and GTEx datasets." (PMID 39114022, 2024). "This is the first report of methylation in any cancer for five loci (CPVL, HOXC9, PAX8, PTPRN2, and SLC38A4), flagging these loci as potential novel cancer markers." (PMID 18616821, 2008). "Data from the human Cancer Cell Line Encyclopedia (CCLE) demonstrated differential expression of these genes across cell lines, with high expression of PHGDH, PSAT1, SLC1A5 and SLC38A2, and low expression of SLC38A4 and SLC7A10." (PMID 40660426, 2025). "In addition, three loci (BC008699, SLC38A4 and LHX1) showed low frequencies of the methylation levels, similar to those observed in cancer tissue." (PMID 24490656, 2014).
SLC38A4 also shares sentences with these, for which no sentence is quoted: adenoma (1 paper); breast adenocarcinoma (1); head and neck squamous cell carcinoma (1); infection (1); Intrauterine Growth Restriction (1); metabolic disease (1); migraine (1); prostate carcinoma (1); rectum adenocarcinoma (1); Stomach Adenocarcinoma (1).